CASP8 (caspase 8)
Diseases named in the same sentence as CASP8 in open-access papers (continued):
Sharing a sentence is not in itself a finding about the gene and the disease.
neuroblastoma (continued). "Lake of expression of caspase 8 is frequent in the several kinds of tumor models such as lung carcinoma, neuroblastoma and hepatocellular carcinoma." (PMID 36832063, 2023). "Caspase-8 expression is decreased in neuroblastoma, small cell lung carcinoma, brain tumors such as medulloblastoma and glioblastoma, liver, breast, prostate, stomach and ovary tumors." (PMID 37444381, 2023). "Further studies in this regard led Cui and colleagues to establish a link between MYCN and the death receptor apoptotic pathways (involves Caspase-8) in neuroblastoma." (PMID 37274289, 2023). "The genomic function of ATRA involves CREB-phosphorylation-dependent caspase-8 transcription leading to neuroblastoma cell apoptosis." (PMID 38249515, 2023). "Knockdown of caspase-8 at mRNA and protein levels was observed in small-cell lung cancers, pediatric neuroblastoma, and neuroendocrine lung cancers." (PMID 37736508, 2023). "They concluded that epigenetic silencing and allelic imbalance are two important mechanisms for the inactivation of Caspase-8 in neuroblastoma." (PMID 37274289, 2023). "Tumors such as medulloblastoma, neuroblastoma and small cell lung cancer, decrease Caspase-8 expression as a way of escaping the apoptotic form of death that regulates healthy tissue homeostasis." (PMID 37444381, 2023). "They provided evidence that Caspase-8 act as a as a metastasis suppressor gene and regulated the survival and invasive capacity of neuroblastoma cells." (PMID 37274289, 2023). "Takita and colleagues demonstrated a common region of allelic imbalance on chromosome 2q and an alteration of CASP8 in neuroblastoma." (PMID 37274289, 2023). "The generation of a neuroblastoma mouse models with caspase-8 deletion in the neural crest lineage, showed increased metastases in the bone marrow, compared to caspase-8 wild-type neuroblastoma mice." (PMID 33026575, 2021). "CASP8 (located on human chromosome 2 band q33) methylation was first reported in neuroblastoma tumors nearly 18 years ago." (PMID 33381579, 2020). "In this regard Caspase-8 is often lost in neuroblastoma and this event accounts for the impairment of IMD and promotes metastatization." (PMID 30501030, 2018). "Caspase-8 has been reported to be deleted frequently or silenced in neuroblastoma tumors and in cell lines including NB-7, NB-8, and NB-10." (PMID 29278364, 2017). "Although most human neuroblastoma cells exhibit drug resistance because of their low levels of caspase-8 expression, previous reports have shown that TRAIL-receptor 2 (TRAIL-R2/DR5/TNFRSF10b) is an important upstream effector of caspase-8." (PMID 29113358, 2017). "NB7 neuroblastoma cells were chosen for these experiments because they lack expression of caspase-8 and hence are completely resistant to the apoptosis-inducing effects of CD95L." (PMID 29063830, 2017). "Complementarily, in a very recent approach, CASP8 302His was associated with worse overall and event-free survival in patients with MYCN-amplified neuroblastoma tumors." (PMID 27507139, 2016). "For instance, caspase 8 is often silenced in neuroblastoma, and in TH-MYCN mice, which express MYCN in neural crest cells that form neuroblastomas; caspase 8 deficiencies cause formation of metastatic neuroblastomas in the bone marrow." (PMID 26859456, 2016). "A missense SNP in exon 10 of the CASP8 gene SNP D302H was associated with worse overall and event-free survival in patients with MYCN-amplified neuroblastoma tumors." (PMID 25502557, 2014). "4-HPR, IFN-γ, and demethylating agent 5-aza-cytidine activate the promoter region of caspase-8 in neuroblastoma cells and regulate both constitutive and inducible caspase-8 expression in pathophysiological condition." (PMID 21876694, 2012). "Genomic action of ATRA includes caspase-8 transcription via CREB-phosphorylation leading to apoptosis in neuroblastoma cells." (PMID 21876694, 2012).
neuroblastoma (continued). "While deletion of CASP8 is common in neuroblastoma resulting in reduced expression and sensitivity to TRAIL, these genomic changes are not common in RMS or EWS." (PMID 22577581, 2012). "Caspase 8 (CASP8) is hypermethylated and thereby inactivated in some neuroblastoma resulting in an inactive extrinsic apoptotic pathway." (PMID 22788920, 2012). "This is an interesting parallel to the putative role caspase-8 plays in invasion and metastasis of neuroblastoma cells." (PMID 24281211, 2010). "Caspase-8 was suggested in several studies to function as a tumour suppressor in neuroblastomas and in lung cancer." (PMID 20221256, 2010). "Conversely, in neuroblastoma caspase-8 gene methylation correlated with amplification of the MYCN gene, whereas caspase-8 protein was absent in the majority of tumors irrespective of MYCN amplification." (PMID 24281211, 2010). "Overexpression of a catalytically inactive caspase-8 mutant was shown to confer migratory and metastastic behavior to neuroblastoma cells." (PMID 24281211, 2010). "Caspase-8 sensitized the neuroblastoma cells to apoptosis specifically once they invaded the stroma but not within the primary tumor." (PMID 24281211, 2010). "Previously, restoration of caspase-8 expression by demethylation or gene transfer was shown to sensitize neuroblastoma cells to DR-mediated apoptosis." (PMID 20416058, 2010). "Jude Children's Research Hospital, Memphis) for the caspase-8 deficient and reconstituted NB7 neuroblastoma cell lines." (PMID 19440351, 2009). "We treated caspase-8 deficient and reconstituted NB7 neuroblastoma cell lines with the antibiotics for 24 hrs." (PMID 19440351, 2009). "Prediction targets of has-miR-196a, a metastatic suppressor gene-CASP8 observed in neuroblastoma cells." (PMID 19898689, 2009). "We found CASP8 promoter methylation in 60% of the neuroblastic tumors and in 92% of the neuroblastoma cell lines." (PMID 17064406, 2006). "Eleven (92%) of the 12 neuroblastoma cell lines studied showed hypermethylation of the CASP8 promoter." (PMID 17064406, 2006). "The best known apoptotic defect in neuroblastoma tumors and cell lines is the down regulation of CASP8, which strongly correlates with TRAIL unresponsiveness." (PMID 17064406, 2006). "We studied the expression of the RASSF1A, BLU, NORE1A and CASP8 genes in 12 neuroblastoma cell lines by semi-quantitative RT-PCR." (PMID 17064406, 2006). "In our study, we examined the methylation status of the RASSF1A, BLU, NORE1A and CASP8 genes in 41 neuroblastic tumors and in 12 neuroblastoma cell lines." (PMID 17064406, 2006). "Recent work shows that expression of caspase-8 is lost in a high number of childhood neuroblastomas." (PMID 11953820, 2002). "Furthermore, interferon-γ (IFNγ) treatment of caspase 8 deficient cells restored caspase 8 expression and TRAIL sensitivity in TRAIL-resistant medulloblastoma and neuroblastoma cell lines." (PMID 35568716, 2022). "Additionally, loss or silencing of caspase 8 expression is associated with MYCN-amplified and aggressive neuroblastomas." (PMID 35568716, 2022). "Similarly, the low expression of caspase-8 in neuroblastoma with N-MYC amplification and small cell lung carcinoma and somatic mutations in CASP8 hepatocellular carcinoma are all associated with increased tumorigenesis." (PMID 35741016, 2022). "In this respect, TLR3-induced LMP, which occurs independently of Caspase-8, could represent a novel therapeutic strategy for cancers which silence Caspase-8 expression, like for example neuroblastoma." (PMID 34011952, 2021). "Although there was a report that Daxx cannot mediate Fas-induced apoptosis, other researchers considered that, owing to the increased signals in cleaved caspase-8, Fas–Daxx interaction can have a proapoptotic effect in mouse motor neuron-neuroblastoma hybrid cells." (PMID 32782452, 2020). "Hypermethylation or genomic deletions in CASP8 gene were also identified in neuroblastoma." (PMID 31652776, 2019).
neuroblastoma (continued). "Our observations have important ramifications, as they may help to explain why Casp8 is frequently lost in several kinds of human tumors, including small-cell lung carcinoma, neuroblastoma, hepatocellular carcinoma, and others." (PMID 30598363, 2019). "Indeed, the restoration of Caspase 8 expression sensitized Neuroblastoma cells to death receptor signaling and cytotoxic drugs." (PMID 31178872, 2019). "Indeed Caspase-8 is genetically or epigenetically silenced in several tumors such as neuroblastoma and medulloblastoma." (PMID 30501030, 2018). "Thus far, we have shown that CHERP depletion can induce neuroblastoma cell apoptosis and increase the expression of cleaved caspase-3 and cleaved caspase-8 expression." (PMID 29113358, 2017). "Previous studies have suggested that caspase-8 might act as a tumour suppressor in certain types of lung cancer and neuroblastoma." (PMID 27798717, 2017). "Caspase-8 represents a typical target for cancer therapy by acting though the Aza-induced restoration of its expression, and its silencing has been reported in neuroblastoma e medulloblastoma, for instance." (PMID 26143641, 2015). "Moreover, BIX-01294 can induce apoptosis in human neuroblastoma cells by raising CASP8 and CASP3 activity." (PMID 25685062, 2015). "We performed also multivariate Cox proportional hazard analysis and investigated the effect of CASP8 SNP D302H on the survival of neuroblastoma patients taking into account the different clinical covariates (stage of the disease, MYCN status, and the age at diagnosis)." (PMID 25502557, 2014). "We recently provided evidence that the FOXO3-ATM complex also overcomes epigenetic silencing of the caspase-8 gene in human neuroblastoma cells by activating the ATM downstream target CREB which in turn triggers methylation-independent activation of the caspase-8 promoter." (PMID 23801966, 2013). "In addition, genomic deletions or silencing of CASP8 are frequent in neuroblastoma with MYC amplification." (PMID 22577581, 2012). "The objective of our screen was to show that compounds that sensitize cells to TRAIL-mediated death, and whose mechanism involves caspase-8 in some way, could be identified by screening the three neuroblastoma lines in parallel and in the presence of TRAIL." (PMID 20967281, 2010). "In experiments using chicken embryos, loss of caspase-8 did not enhance the growth of tumors formed by xenotransplanted human neuroblastoma cell lines, however, was essential for their invasion and metastasis formation." (PMID 24281211, 2010). "Besides, it has been also shown that caspase-8 expression is lost or inactivated in certain types of cancer such as small cell lung cancer, neuroblastoma, gastric carcinoma and hepatocellular carcinoma." (PMID 20808443, 2010). "Therefore, the DEDs of caspase-8 appeared to influence both, multinucleation and the acquisition of cellular differentiation in the neuroblastoma cell model." (PMID 19924290, 2009). "The present study shows that the downregulation of caspase-8 plays a role in resistance of metastatic neuroblastoma to apoptosis, which could be reversed by 4-HPR treatment." (PMID 19331667, 2009). "The main apoptotic defect found in neuroblastomas is the down-regulation of the CASP8 gene." (PMID 17064406, 2006). "Our results suggest that: 1) LOH at 3p21 appears in a small percentage of neuroblastomas, suggesting that a candidate tumor suppressor gene of neuroblastic tumors is not located in this region, and 2) promoter hypermethylation of RASSF1A and CASP8 is frequent in neuroblastomas." (PMID 17064406, 2006). "Thus, CASP8 promoter methylation has been reported in ∼50% of neuroblastomas by us and other and RASSF1A promoter methylation also occurs frequently (52–55%." (PMID 15505628, 2004). "Therefore, we used apoptosis-resistant neuroblastoma (Kelly) cells defective in death receptor signalling due to a hypermethylated and downregulated caspase-8 gene." (PMID 14647152, 2003).
neuroblastoma (continued). "Indeed, caspase 8 promoter methylation and subsequent silencing are associated with tumour aggressiveness in ganglioneuromas, and with invasiveness in TRAIL-resistant neuroblastoma cell lines." (PMID 35568716, 2022). "Additionally, caspase-8 has been observed to be recruited and localized to leading lamellae in endothelial cells, as well as the leading edge of actin-based lamellae at focal adhesion complexes in neuroblastoma cells." (PMID 29854765, 2018). "Moreover cytochrome c release was observed in caspase 8 deficient neuroblastoma cells IMR32 (Data not shown)." (PMID 23593137, 2013). "Absent or downregulation of CASP8 could cause resistance to apoptosis and is correlated with unfavorable disease outcome, such as in childhood medulloblastoma and neuroblastoma." (PMID 20132554, 2010). "For example, CASP8, on 2q33, was one of the first genes found to be methylated in neuroblastoma, with a frequency of about 40 % in primary NB tumours." (PMID 15740626, 2005). "SAHA-treated neuroblastoma cells demonstrated dose-dependent decreases in the levels of Ku70 and c-FLIPL, with induction of caspase 8 activation and PARP cleavage indicative of induction of apoptosis." (PMID 37957138, 2023). "In vitro treatment with 5-Aza-2’-deoxycytidine, a demethylating agent, successfully restored caspase 8 expression and sensitivity to TRAIL-induced apoptosis in cell line models of PNET, neuroblastoma and medulloblastoma." (PMID 35568716, 2022). "Increased methylation of the caspase 8 promoter mediates its transcriptional silencing in medulloblastoma, PNET, and neuroblastoma." (PMID 35568716, 2022). "Our microarray-based gene expression profiling data demonstrated that CASP8 and CASP3 mRNA expression increased upon exposure of SH-SY5Y neuroblastoma cells to CDDP." (PMID 28206967, 2017). "In brief, NF-κB mediates Fas-induced cell apoptosis via regulating caspase-4, which transduces death signal from caspase-8 to caspase-3 and PARP in neuroblastoma cells." (PMID 25695505, 2015). "Earlier reports showed BIX-01294 led to apoptosis by activating CASP8 and CASP3 in human neuroblastoma cells and reduce the proliferation of human bladder cancer cells." (PMID 25685062, 2015). "We observed the expressions of caspase-3, caspase-8, and caspase-9 in the untreated SH-SY5Y neuroblastoma cells, which corroborated previous reports." (PMID 26664453, 2015). "Moreover, the methylation status of CASP8 and HIC1 was significantly correlated in both neuroblastomas and phaeochromocytomas, with CASP8 methylation observed exclusively in tumors exhibiting HIC1 methylation." (PMID 40558831, 2025). "However, in several other cancer types, the CASP8/MCL-1 mRNA ratio did significantly correlate with sensitivity to MEDI3039: ovarian cancer, small-cell lung cancer, neuroblastoma, DLBCL, bladder and skin cancers." (PMID 35086954, 2022). "When TLR3 was activated in the Caspase-8 negative neuroblastoma cell line SH-SY5Y, cell death was accompanied by lysosomal permeabilization." (PMID 34011952, 2021). "Treatment of platelets with anti-Fas antibodies did not induce caspase-8 activation, but activated platelets express the membrane bound ligand FasL, and can activate caspase 3/7 in human neuroblastoma cells and mouse embryonic fibroblasts." (PMID 33428668, 2021). "The resistance of neuroblastoma cells to apoptosis induced by TNF, tumor necrosis factor-related apoptosis-inducing ligand (TRAIL), and cytotoxic agents such as doxorubicin, has been attributed to a lack or diminished expression of caspase-8." (PMID 29278364, 2017). "No detectable expression of caspase-8 was also observed both in the human neuroblastoma cells and rat cortical neurons." (PMID 27377128, 2016). "Metastasis formation of non-apoptotic neuroblastoma cells was enhanced by recruitment of caspase-8 to the cellular migration machinery." (PMID 24209510, 2013).
neuroblastoma (continued). "It was suggested that the addition of DNA methyltransferase inhibitors, such as 5-dAzaC, may restore CASP8 expression and sensitize resistant cells to TRAIL-induced apoptosis in some neuroblastoma and medulloblastoma cells." (PMID 22577581, 2012). "Inactivation of caspase-8 by hypermethylation of regulatory sequences of the caspase-8 gene occurs in several human cancers in addition to RMS, for example, in neuroblastoma, medulloblastoma, Ewing tumors, and small-cell lung cancer both in cell lines as well as in primary tumor samples." (PMID 22294874, 2012). "Utilization of the caspase-8 null neuroblastoma cell line, NB7, and the same line reconstituted with either wild-type or a catalytically inactive point mutant of caspase-8 (C360A) in parallel allows the identification of chemical agents that act specifically via the caspase-8 apoptotic pathway." (PMID 20967281, 2010). "Also, xenografts of neuroblastoma cells with a defective caspase-8 gene did not respond to TRAIL." (PMID 14647152, 2003). "As well, lack of expression of caspase 8 has been documented as a resistance approach to TRAIL and chemotherapy in neuroblastoma cells." (PMID 36832063, 2023). "Activation of TLR3 triggers the extrinsic apoptotic pathway with Caspase-8 as an apical caspase in the Caspase-8 positive, RIPK3 negative Neuroblastoma cell line, SK-N-AS6." (PMID 34011952, 2021). "The DEDs of caspase-8, but not c-FLIP, interact with stable microtubule structures, including centrosomes, spindle poles and midbodies in neuroblastoma cells as well as keratinocytes and other epithelial cells." (PMID 19924290, 2009). "In neuroblastoma cells, treatment with IFN-γ can induce methylation-silenced caspase-8 expression without affecting the methylation status within the promoter region." (PMID 17376236, 2007).